TAF11L4 (TATA-box binding protein associated factor 11 like 4)
Gene: Protein-coding gene on chromosome 5 (17,521,801 to 17,522,397, forward strand). Ensembl gene ENSG00000284283.
Gene Ontology:
Molecular function: RNA polymerase II general transcription initiation factor activity; protein heterodimerization activity
Biological process: RNA polymerase II preinitiation complex assembly; transcription initiation at RNA polymerase II promoter
Cellular component: transcription factor TFIID complex; nucleus
Homologues: Orthologues: tropical clawed frog taf11 (46% identical), zebrafish taf11 (45% identical), Drosophila melanogaster Taf11 (42% identical), Caenorhabditis elegans taf-11.1 (33% identical), Caenorhabditis elegans taf-11.2 (27% identical). Paralogues in human: TAF11L10 (99% identical), TAF11L5 (99% identical), TAF11L6 (99% identical), TAF11L7 (99% identical), TAF11L8 (99% identical), TAF11L3 (99% identical), TAF11L9 (99% identical), TAF11L13 (94% identical), TAF11L2 (91% identical), LINC02218 (87% identical), TAF11L12 (87% identical), TAF11L11 (84% identical), and 2 more.